RBFOX2 (RNA binding fox-1 homolog 2)
Diseases named in the same sentence as RBFOX2 in open-access papers (continued):
Sharing a sentence is not in itself a finding about the gene and the disease.
diabetic cardiomyopathy (3 papers, 2021 to 2022). Diabetic cardiomyopathy is a disorder of the heart muscle in people with diabetes. "RBFox2 regulates cardiac function-related genes associated with diabetic cardiomyopathy." (PMID 36277184, 2022). "Low activity of RBFOX2 inhibits RBFOX2-dependent splicing and affects the processing of calcium ions by cardiomyocytes, ultimately leading to the development of diabetic cardiomyopathy." (PMID 35597446, 2022). "Dominant negative RBFox2 expression is exclusive to diabetes and appears in its early stages, therefore it might be served as a potential target for treating diabetic cardiomyopathy." (PMID 36277184, 2022). "For instance, RNA Binding Fox-1 Homolog 2 (RBFOX2), regulates alternative splicing and is upregulated in the diabetic heart, controlling splicing of genes involved in diabetic cardiomyopathy by binding to target RNA motifs associated with protein trafficking and cell apoptosis." (PMID 33923168, 2021). "However, the mechanism by which RBFOX2 causes diabetic cardiomyopathy is still not fully understood, and the relationship RBFOX2 and its dominant-negative levels is not yet elucidated." (PMID 35597446, 2022). "Besides, another study indicated that CUG-BP (also known as CELF1)/RBFox2 can be phosphorylated and up-regulated by activating PKC signaling in diabetic heart, which in turn alters the AS of gene and contribute to diabetic cardiomyopathy pathogenesis." (PMID 36277184, 2022).
glioma (3 papers, 2014 to 2024). A benign or malignant brain and spinal cord tumor that arises from glial cells (astrocytes, oligodendrocytes, ependymal cells). "Moreover, in glioma, RBFOX2 expression is lower in lesion brain tissue of glioma patients compared to normal brain tissue, and within glioma patients, those with higher malignancy exhibit lower RBFOX2 expression in lesion brain tissue than those with less malignancy." (PMID 39243148, 2024).
hepatocellular carcinoma (3 papers, 2018 to 2024). A malignant tumor that arises from hepatocytes. "To validate the role of FOXA1/2 in Rbfox2 regulation, we knocked down Foxa1 and Foxa2 in mouse hepatoma Hepa1-6 cells, which led to a significant decrease in Rbfox2 expression." (PMID 36536133, 2022). "Notably, we observed lower levels of RBFOX2 in tumor tissues of hepatocellular carcinoma (HCC) patients compared to paired adjacent tissues." (PMID 38881877, 2024). "Interestingly, RBFOX2 expression was found to be lower in hepatocellular carcinoma (HCC) patients’ tumor tissues compared to their paired adjacent tissues." (PMID 38881877, 2024).
schizophrenia (3 papers, 2021 to 2022). A major psychotic disorder characterized by abnormalities in the perception or expression of reality. "Candidate gene analysis highlighted enrichment for 15 gene sets, including neuronal and synaptic processes, schizophrenia genetic risk, and RBFOX2, a key regulator of splicing within the nervous system and of estrogen receptor transcriptional activity." (PMID 33279206, 2021). "Although BD shares common variant heritability with schizophrenia, in the BSC sample we did not observe a significant enrichment of P-LP variants in SCZ GWAS genes, in two classes of neuronal synaptic genes (RBFOX2 and FMRP) associated with SCZ or in loss-of-function intolerant genes." (PMID 33483695, 2021).
acute myeloid leukaemia (2 papers, 2023 to 2024). "Functional analysis of genes harbouring m6A and bound by RBFOX2 at their promoters highlights pathways related with both chronic and acute myeloid leukaemia." (PMID 37640841, 2023). "Downregulation of RBFOX2 notably inhibits survival/proliferation of acute myeloid leukaemia cells and promotes their myeloid differentiation." (PMID 37640841, 2023). "When RBFOX2 acts as a reader of m6A, it plays an important role in acute myeloid leukaemia (AML)." (PMID 39243148, 2024). "The RBFOX2/m6A/RBM15/YTHDC1/PRC2 axis plays an important role in myeloid leukaemia, with downregulation of RBFOX2 notably inhibiting acute myeloid leukaemia (AML) cell survival/proliferation and promoting myeloid differentiation of AML cells." (PMID 37640841, 2023).
Arrhythmia (2 papers, 2018 to 2024). Any cardiac rhythm other than the normal sinus rhythm. "Similarly, loss-of-function mutations in the rbFOX2 gene are responsible for developmental cardiac alterations, which are different from the adult-onset progressive cardiac conduction defects and arrhythmias observed in individuals with myotonic dystrophy." (PMID 29789616, 2018).
colorectal cancer (2 papers, 2024). A primary or metastatic malignant neoplasm that affects the colon or rectum. "In this paper, we found, that in colorectal cancer cells, the long non-coding RNA H19 can bind immature RNAs and splicing factors as hnRNPM and RBFOX2." (PMID 39098911, 2024).
Ewing sarcoma (2 papers, 2021 to 2024). A small round cell tumor that lacks morphologic, immunohistochemical, and electron microscopic evidence of neuroectodermal differentiation. "To test this hypothesis, we first evaluated whether EWS-FLI1 associates with RBFOX2 in Ewing sarcoma cells." (PMID 34009296, 2021). "As observed in HeLa and HUVEC cells, ASEs accounted for the majority of splicing events regulated in Ewing sarcoma cells following RBFOX2 knockdown (74,1%, 569/768)." (PMID 34009296, 2021). "To further support a functional link between EWS-FLI1 and RBFOX2, we analyzed splicing changes following RBFOX2 depletion in A673/TR/shEF Ewing sarcoma cells." (PMID 34009296, 2021). "Altogether, these data indicate that EWS-FLI1 and RBFOX2 interact with each other, and regulate a common set of ASEs in Ewing sarcoma cells, either in a similar or opposite manner." (PMID 34009296, 2021). "By RT-PCR, we verified that EWS-FLI1 promotes the ADD3-L isoform, which contains exon 14, whereas RBFOX2 reduces the inclusion of exon 14 of ADD3 in Ewing sarcoma cells." (PMID 34009296, 2021). "Moreover, in the Ewing's sarcoma cell line (A673), RBFOX2 has been found to bind to ADD3 (a phenotypic driver of Ewing's sarcoma) pre‐mRNA." (PMID 39243148, 2024). "Based on our observation that EWS-FLI1 represses a large subset of RBFOX2-regulated ASEs, we thus hypothesized that EWS-FLI1 might inhibit specific RBFOX2-dependent ASEs to antagonize mesenchymal features in Ewing sarcoma cells." (PMID 34009296, 2021). "Co-immunoprecipitation experiments in A673/TR/shEF, a well-characterized Ewing sarcoma cell line, revealed the presence of EWS-FLI1 in endogenous RBFOX2 complexes." (PMID 34009296, 2021). "Our findings reveal a RBFOX2-mediated splicing regulatory function of wild-type ERG family proteins, that is altered in EWS-FLI1 and contributes to the Ewing sarcoma cell phenotype." (PMID 34009296, 2021). "The observation that RBFOX2 binding to its target pre-mRNA, ADD3 is increased after depletion of EWS-FLI1 in Ewing sarcoma cells, suggests that EWS-FLI1 expression may interfere with RNA binding by RBFOX2." (PMID 34009296, 2021).
Hypertension (2 papers, 2022 to 2024). The presence of chronic increased pressure in the systemic arterial system. "Consequently, dysregulation of Rbfox2's influence on Cav1.2 channel function emerges as a key contributor to hypertension pathogenesis." (PMID 39243148, 2024).
laryngeal carcinoma (2 papers, 2024). Carcinoma that arises from the laryngeal epithelium. "Laryngeal carcinoma cells (Tu177, M4E, Hep2 and Tu212) show elevated RBFOX2 expression relative to normal nasopharyngeal epithelial cells (NP69) in laryngeal cancer." (PMID 39243148, 2024). "Silencing RBFOX2 also significantly inhibited cell proliferation and invasion in laryngeal cancer by mediating MENA alternative splicing." (PMID 38881877, 2024). "There have been reports on the enhancement of laryngeal cancer cells’ metastasis through the upregulation of RBFOX2, achieved by skipping exon 11a of MENA." (PMID 38881877, 2024). "Elevated RBFOX2 promotes the skipping of MENA exon 11a, ultimately stimulating proliferation, EMT, and invasion of laryngeal cancer cells." (PMID 39243148, 2024). "In laryngeal cancer cells (Tu177 and Hep2), the upregulated lncRNA ZFAS1 binds to and upregulates RBFOX2 expression." (PMID 39243148, 2024).
liver cancer (2 papers, 2020 to 2024). An epithelial or non-epithelial malignant neoplasm that arises from the liver. "In vitro studies have shown that knockdown of RBFOX2 significantly promotes the growth and metastasis of liver cancer cells." (PMID 38881877, 2024). "In vitro experiments provided evidence that knocking down RBFOX2 significantly increased the growth and metastasis of liver cancer cells." (PMID 38881877, 2024). "All in all, our discoveries suggested that RBFOX2 assumes a function in impeding the progression and metastasis of liver cancer cells in vitro." (PMID 38881877, 2024). "This study investigates the correlation between DNA methylation, prognostic value, and immune cell infiltration with the expression of RBFOX2 in pan-cancer and indicates its potential role to inhibit metastasis of liver cancer." (PMID 38881877, 2024). "At the end, we check the function of RBFOX2 to clarify the role in human liver cancer cells (Hep G2)." (PMID 33179042, 2020). "Notably, knockdown of RBFOX2 led to an increase in colony numbers and enhanced proliferation of liver cancer cells." (PMID 38881877, 2024). "Furthermore, previous studies have identified RBFOX2 as a key splicing factor in hepatitis C virus (HCV) related liver cancer." (PMID 38881877, 2024). "Additionally, qRT-PCR, CCK-8, colony formation, transwell assays, and immunohistochemistry were employed to analyze the expression and biological function of RBFOX2 in liver cancer." (PMID 38881877, 2024). "Moreover, our study firstly revealed that knockdown of RBFOX2 could promote the proliferation and metastasis of HCC cells in vitro, indicating that RBFOX2 functions as a suppressor gene for liver cancer." (PMID 38881877, 2024).
myotonic dystrophy 1 (2 papers, 2023 to 2024). "A recent report demonstrated that a non-muscle isoform of RBFOX2 [RBFOX240] is upregulated in heart tissue from myotonic dystrophy 1 (DM1) patients leading to elevated CELF1 and a global miRNA suppression." (PMID 36675070, 2023).
nasopharyngeal carcinoma (2 papers, 2024). A carcinoma arising from the nasopharyngeal epithelium. "RBFOX2 has been reported to alter the splicing of GOLIM4 in nasopharyngeal carcinoma." (PMID 38881877, 2024). "The mRNA level of RBFOX2 was significantly upregulated in nasopharyngeal carcinoma (NPC) tissues, correlating with the initiation of NPC cell tumorigenesis." (PMID 38881877, 2024).
neuroblastoma (2 papers, 2017 to 2021). Neuroblastoma (NB) is the most common solid, extracranial childhood tumor. "We used the F11 cell line (DRG/neuroblastoma fusion) because it expresses endogenous CaV2.2 and Rbfox2, and these cells are relatively easy to transfect with high efficiency, facilitating biochemical and RT-PCR analyses." (PMID 29067356, 2017).
Obesity (2 papers, 2022 to 2024). Accumulation of substantial excess body fat. "RBFOX2 function is decreased in the liver in diet-induced obesity, causing a Scarb1 isoform switch and alteration of hepatocyte lipid homeostasis." (PMID 36536133, 2022). "Western blot analysis showed that both HFD- and HFr-diet-induced obesity are associated with decreased expression of the main RBFOX2 isoform in the liver." (PMID 36536133, 2022).
prostate carcinoma (2 papers, 2017 to 2019). A carcinoma that arises from epithelial cells of the prostate gland. "Consistently, digitoxin is also able to significantly suppress mRNA expression for both HSPB1, a biomarker for EMT in prostate cancer, and the HSPB1/RBFOX2 ratio." (PMID 31428571, 2019). "Interestingly, recent data points to a key role for RBFOX2 and MBNL1 who seem to account for numerous splicing alterations in various cancers including breast, lung, and prostate cancer." (PMID 28493890, 2017).
Rolandic epilepsy (2 papers, 2013 to 2014). "In this study, we explored if structural microdeletions and exonic sequence variations in RBFOX1, RBFOX2, RBFOX3 confer susceptibility to rolandic epilepsy (RE), a common idiopathic focal childhood epilepsy." (PMID 24039908, 2013). "The high comorbidity between Rolandic Epilepsy and RD and the presence of a FOXP2 binding site ∼5 kb from rs5995177, further support a link of RBFOX2 with reading and language abilities." (PMID 25065397, 2014).
Anxiety (1 paper, 2017). Intense feelings of nervousness, tension, or panic often arise in response to interpersonal stresses. "Rbfox2 is upregulated in the brain of patients with bipolar disorders and mice with high anxiety-like behavior." (PMID 29375311, 2017).
cervical carcinoma (1 paper, 2017). A carcinoma arising from either the exocervical squamous epithelium or the endocervical glandular epithelium. "Rbfox2 is predominantly localized in the nucleus, as seen in human cervical carcinoma HeLa cells." (PMID 28894257, 2017).
chronic myelogenous leukaemia (1 paper, 2023). "While investigating the role of RBFOX2 in K562 (a chronic myelogenous leukaemia cell line) cells, we found that RBFOX2 depletion led to a noticeably reduced colony forming ability and impaired cell growth." (PMID 37640841, 2023).
clear cell renal cell carcinoma (1 paper, 2025). "In clear cell renal cell carcinoma, alternative splicing of PBRM1 exon 27, mediated by RBFOX2, influences resistance to PD-1 blockade therapy." (PMID 40909272, 2025).
complication (1 paper, 2017). Any disease or disorder that occurs during the course of, or because of, another disease, treatment, or procedure. "DN-RBFOX2 precedes diabetic cardiac complications, as well as delays intracellular calcium transients in cardiomyocytes by blocking RBFOX2-mediated alternative splicing." (PMID 28811863, 2017).
dyslexia (1 paper, 2018). A learning disorder characterized by an impairment in processing written words. "However, it is worth noting that GWAS for dyslexia have been under‐powered so far and variants with the strongest association to dyslexia (e.g., in genes RBFOX2, ABCC13, ZNF385D, COL4A2 and FGF18) failed to survive genome‐wide statistical scrutiny." (PMID 30218584, 2018).
hypospadias (1 paper, 2022). Hypospadias is the displacement of the urethral meatus on the ventrum of the penis. "We also identified SROs overlapping with the following genes with established associations with hypospadias: RBFOX2, SHH, and WT1." (PMID 35457073, 2022).
insulinoma (1 paper, 2023). "To distinguish β cell-specific altered splicing events and to establish a cell system that would allow us to probe the molecular activity of RBFOX2, we also took a siRNA approach to knockdown Rbfox2 in the mouse-insulinoma cell line (MIN6)." (PMID 38007492, 2023).
lymphoma (1 paper, 2024). A malignant (clonal) proliferation of B- lymphocytes or T- lymphocytes which involves the lymph nodes, bone marrow and/or extranodal sites. "In lymphoma, RBFOX2 expression significantly surpasses that in primary human T cells, as evidenced by its higher levels in human lymphoma cells (Karpas299 and Jurkat)." (PMID 39243148, 2024).
malignant glioma (1 paper, 2021). A grade III or grade IV glioma arising from the central nervous system. "Our analysis on malignant glioma patient samples demonstrate that the level of RBFOX2 expression is not altered in these patients, but, surprisingly, RBFOX2-mediated exon inclusion events are diminished in GBM patients." (PMID 34548489, 2021).
myeloid leukaemia (1 paper, 2023). "To better characterize how RBFOX2 regulates myeloid leukaemia via m6A, we correlated the expression changes of the genes co-occupied by RBFOX2 and RBM15 in either RBFOX2 KD or RBM15 KD K562 cells, and found a positive correlation, as expected." (PMID 37640841, 2023). "Furthermore, we found that this RBFOX2/m6A/RBM15/YTHDC1/PRC2 axis plays a critical role in myeloid leukaemia." (PMID 37640841, 2023).
myocardial infarction (1 paper, 2024). Gross necrosis of the myocardium, as a result of interruption of the blood supply to the area, as in coronary thrombosis. "Myocardial infarction–associated transcript (MIAT) was shown to bind and stabilize RNA-binding fox-1 homolog 2 (RBFOX2) protein, thereby promoting RBFOX2-induced upregulation of MCL-1L and reduction of pro-apoptotic MCL-1S." (PMID 39695189, 2024).
Myotonia (1 paper, 2025). An involuntary and painless delay in the relaxation of skeletal muscle following contraction or electrical stimulation. "Interestingly, several splicing factors including Srsf6, Prpf39, Rbm7, Tra2b, Rbfox2, and Hnrnpu, exhibited alternative splicing in Mbnl1−/− mice with myotonia, but not in those without." (PMID 41000779, 2025).
myotonic dystrophy (1 paper, 2018). An inherited progressive disorder affecting the muscles. "In mouse models, knockout for rbFox1 or rbFox2 present severe skeletal muscle, heart and brain dysfunctions, which are different from the alterations observed in myotonic dystrophy." (PMID 29789616, 2018).
myotonic dystrophy type 2 (1 paper, 2018). Myotonic dystrophy type 2 (MD2), also known as proximal myotonic myopathy, is a very rare genetic multi-system disorder of late childhood or adult-onset characterized by mild myotonia, muscle weakness, and rarely cardiac conduction disorders. "Overall, these data indicate that rbFOX1 and rbFOX2 are specific components of CCUG RNA foci in myotonic dystrophy type 2." (PMID 29789616, 2018).
Parkinson disease (1 paper, 2023). A progressive degenerative disorder of the central nervous system characterized by loss of dopamine producing neurons in the substantia nigra and the presence of Lewy bodies in the substantia nigra and locus coeruleus. "Herein, it is revealed that FBXO7, a substrate‐recognition component of the SCF complex implicated in the pathogenesis of Parkinson's disease, confers mesenchymal properties and chemoresistance in GBM by controlling Rbfox2‐mediated alternative splicing." (PMID 37822160, 2023).
testicular embryonic carcinoma (1 paper, 2024). "Moreover, lncRNA Gm2044 inhibited the expression of Rbfox2 (a known direct target gene of miR-202) by acting as the host gene of miR-202 and participated in the miR-202-Rbfox2 signaling pathway to inhibit the proliferation of human testicular embryonic carcinoma cells NCCIT." (PMID 39027044, 2024).
Type I diabetes (1 paper, 2022). "RBFOX binding motifs are found to be co-enriched with MBNL and CELF motifs around the same groups of exons in humans, mice and chickens, and CELF2 and Rbfox2 co-regulate exons in cardiac tissue that show temporal use preferences, or are altered in hearts of a Type I diabetes mouse model." (PMID 34996845, 2022).
Wilms tumor (1 paper, 2022). An embryonal neoplasm characterized by the presence of epithelial, mesenchymal, and blastema components. "This might also explain the heterogeneity in expression levels of QKI, and also the fact that unlike ESRP1 and ESRP2, the expression levels of RBFOX2 in the Wilms’ tumor xenograft samples are heterogeneous and not similar to those in hFK1." (PMID 36380228, 2022).